SNORA59B (small nucleolar RNA, H/ACA box 59B)
Synonyms: ACA59
Gene: Small nucleolar RNA gene on chromosome 17 (19,557,211 to 19,557,911, forward strand). Ensembl gene ENSG00000266079.
Gene Ontology:
Biological process: RNA processing
Cellular component: nucleolus